Y_RNA (Y RNA )
Gene: Miscellaneous RNA gene on chromosome 15 (65,502,741 to 65,502,836, forward strand). Ensembl gene ENSG00000252217.
Homologues: Orthologues: chimpanzee Y_RNA (99% identical). Paralogues in human: RNY4 (88% identical), RNY4P19 (88% identical), RNY4P6 (86% identical), RNY4P7 (86% identical), Y_RNA (85% identical), RNY4P10 (84% identical), RNY4P14 (84% identical), Y_RNA (84% identical), RNY4P13 (83% identical), RNY4P17 (83% identical), RNY4P24 (83% identical), RNY4P3 (83% identical), and 88 more.